FOXP3 (forkhead box P3)
Diseases named in the same sentence as FOXP3 in open-access papers (continued):
Sharing a sentence is not in itself a finding about the gene and the disease.
tumor (continued). "Importantly, conditional deletion of Ifng in Foxp3+ Tregs and their progeny partially reverses the antitumor efficacy of OX40/CD137 bispecific agonist therapy, revealing that reprogramming of Tregs into IFNγ-producing cells contributes to the anti-tumor efficacy of OX40/CD137 bispecific agonists." (PMID 38995700, 2024). "We further deepened the concept and found that CCR8+ Treg cells, unlike tradition FOXP3+ Treg cells, displayed high expression of exhaustion and cytokine receptors and strongly correlated with inflammatory response, suggesting its highly activated and tumor-reactive phenotypes." (PMID 38897205, 2024). "However, we did not observe a significant correlation between c-FOXP3+E-Cadherin− cells and the T stage (P = 0.399), suggesting that this cell subtype may not affect the tumor volumes." (PMID 38047300, 2024). "Notably, an obvious decrease in the proportion of regulatory T cells (CD3+CD4+Foxp3+, Tregs) was also seen in the PEG‐CuP‐COF@∆St + US group, demonstrating that PEG‐CuP‐COF@∆St + US‐mediated pyroptosis effectively reduced immunosuppression and remodeled tumor microenvironment." (PMID 39494618, 2024). "Additionally, TIM-3(+) Foxp3 (+) CD4 T cells are preferentially distributed within the tumor nest rather than the peri-tumor matrix, which may contribute to the immunosuppressive tumor microenvironment." (PMID 39206199, 2024). "However, it is known that the CD4+ and CD25+ markers contain populations of Tregs and effector T-cells 6 and Foxp3+ is not restricted to Tregs and may be also activated in other cell types, such as effector T-cells and tumor cells." (PMID 38781760, 2024). "No effectof treatment or tissue type on the expression of FOXP3 in tumor cells could beseen." (PMID 36880147, 2023). "To examine whether baseline tumor-infiltrating immune cells might predict which NSCLCs are more likely to benefit from CRT and durvalumab, we interrogated immune cell subsets of NSCLCs using multiplex immunofluorescence (mIF) platform (ImmunoProfile) which quantifies CD8, FOXP3, PD-1, and PD-L1." (PMID 37454214, 2023). "The cells in seqC1_FoxP3int had a relatively low expression of FoxP3, CD25, CTLA-4, HLA-DR, PD-1 and IL-10, and a high expression of IL-17, indicating that these may be pro-inflammatory Tregs induced in an inflammatory microenvironment in these tumor and lymph node tissues." (PMID 37232845, 2023). "In addition, the ratio of CD4+CD25+Foxp3+ cells was reduced to 56.5% in the tumor tissues of BALB/c mice inoculated with LN229 cells transfected with sh-lncRNA HOXA-AS2, while it was reduced to only 29.2% in tumor tissues of BALB/c mice inoculated with A172 cells transfected with sh-lncRNA HOXA-AS2." (PMID 35181676, 2022). "However, depletion of FoxP3.Luci-DTR Tregs from FoxP3.Luci-DTR + CD27 − / − chimeras by DT injection resulted in a significant reduction in tumor growth and prolonged survival, indicating that CD27 expression on regulatory T cell inhibits immune responses against MC38 tumor cells." (PMID 34423375, 2022). "Our study additionally proposes a possible role for tumors to attract FoxP3+, as well as CD163+ cells, that may afterwards participate in suppression pathways, resulting in the impairment of endogenous antitumor immune responses within the tumor microenvironment." (PMID 36551693, 2022). "On these bases, we would like to propose the hypothetical scenario that the FoxP3+ and CD163+ cells which infiltrate the tumor constitute suppressor circuits, which are, in essence, derived by and are intrinsically linked to the immune system, rather than being organized by the tumor cells." (PMID 36551693, 2022). "However, reports of FOXP3 as a tumor-promoting factor have not been thoroughly validated." (PMID 36522683, 2022).
tumor (continued). "We also observed that TβRII+ EVs could led to a reduced cytotoxicity of tumor-infiltrating T cells (IFNγ+ or GZMB+ of CD8+ cells) and an increased exhaustion of tumor-infiltrating T cells (IFNγ+ or PD1+ of CD8+ cells) and a reduced fraction of FOXP3+ T regulatory cells in doxycycline-treated mice." (PMID 35915084, 2022). "The contradictory observations regarding tumor grading and the amount of CD3+ lymphocyte infiltration could be due to the small number (n = 50) of patients included in our study but also to the fact that the CD4+ FoxP3+ lymphocytes are only a subgroup of lymphocytes." (PMID 35326691, 2022). "Moreover, levels of CD4+PD-1+ T cells were correlated with levels of FoxP3+ Tregs, Helios+ T cells, FoxP3+Helios+ Tregs, FoxP3+Helios− Tregs, and FoxP3−Helios+ T cells in normal tissues, indicating that PD-1 expression is not induced solely by tumor cells." (PMID 35455287, 2022). "The pharmacological treatments available to maintain FOXP3 expression, such as CPG methylation, histone deacetylase inhibitors and the mammalian target of rapamycin (mTOR) inhibitor rapamycin (sirolimus), can result in general immunosuppression, which could lead to tumour relapse and infection." (PMID 34919342, 2021). "To determine whether LFPRLR SMO affected the ability of peripheral Tregs (i.e. those not within the tumor) to suppress effector cell proliferation, we treated non-tumor bearing animals (Foxp3+EGFP Balb/c mice) for up to 5 months with Control SMO or LFPRLR SMO and then isolated splenocytes." (PMID 34375938, 2021). "Furthermore, macrophages and regulatory T lymphocytes probably represent important counter-regulatory mechanisms that the tumor recruits to allow its escape of the adaptive immune response and a high CD8 to FOXP3 ratio in the tumor stroma is a predictor of improved survival in non-metastatic TNBC." (PMID 34362334, 2021). "In the current study, there is a high immune response illustrated by high expression of CD8, FOXP3 and CD68, which play an important role in tumour microenvironment and immune response, to ISG15 protein expression which may also support the role of ISG15 in controlling tumour microenvironment in BC." (PMID 33073304, 2021). "However, here there were also CD20+ cells within vital tumor tissue, while FoxP3 was negative." (PMID 33375357, 2020). "To exert such a powerful prognostic influence on patient outcome, we explored the hypothesis that intra‐tumoral CD4+FOXP3+ T cells in GC interact with other nearby immune effector cells and exert their anti‐tumor effect indirectly rather than via direct tumor cell contact." (PMID 32377339, 2020). "In the current study, FOXP3 expression in PTC was associated with negative prognostic factors such as; large tumor size, bilaterality, multifocality, extracapsular invasion, and the presence of lymph node and distant metastasis, which may have a specific impact on radioiodine sensitivity." (PMID 32606302, 2020). "This was accompanied by changes in the tumor microenvironment: increased matrix deposition (which could contribute to higher p-MLC2) and higher numbers of immunosuppressive populations, in particular CD206+ macrophages and forkhead box P3 (FOXP3+) regulatory T cells (Tregs)." (PMID 32391428, 2020). "The OS T-reg cells expressed the canonical gene signature including the FOXP3 and IL2RA, and they also showed relatively high immune-inhibitory molecules including the CTLA4 and TIGIT, which may contribute to T-reg cell-mediated suppression of anti‐tumor immune responses in OS lesions." (PMID 33303760, 2020). "Notably, the potential role of USP44 as a regulator of the anti‐tumor immune response was not explored in any of these studies, and, indeed, the ability of this and other DUBs to control FOXP3 expression and Treg function in cancer has yet to be explored in detail." (PMID 32644293, 2020).
tumor (continued). "Furthermore, it is noteworthy that FOXP3 functions as dual roles through interaction with other transcription factors nuclear factor kappa-B (NF-κB), nuclear factor of activated T cells (NFAT), and acute myeloid leukemia 1 (AML-1) in the tumor microenvironment." (PMID 31815635, 2019). "We observed a significant increase in Foxp3+ regulatory T cells (Tregs) in the lungs of tumor-bearing mice regardless of erlotinib treatment suggesting that these immunosuppressive cells, which also may play a role in tissue repair, are retained even following erlotinib-mediated tumor regression." (PMID 31291990, 2019). "The relative balance of antagonistic effector (i.e., CD8+ cytotoxic T cells) and regulatory (i.e., FoxP3+ T regulatory cells [Tregs]) immune cell subpopulations may tilt the TME to be either detrimental or supportive of tumorigenesis, and will have a profound impact on the tumor’s eventual destiny." (PMID 31903172, 2019). "A higher CD8A expression was expected, since increased numbers of CD8+, FoxP3+, and CD4+ TILs in HPV-positive vs. HPV-negative OPSCC have been noted earlier, where in particular a higher number of CD8+TILs is linked to a better clinical outcome, irrespective of the HPV status of the tumor." (PMID 29587383, 2018). "The fact that high expression of CCL1 and FoxP3 was found in high-grade tumors again suggests their detrimental effect on prognosis, although we could not find a significant effect on overall survival or tumor-free survival in our analysis." (PMID 30572845, 2018). "Interestingly, we could not find an alteration in Foxp3+ CD4+ previously gated on CD4+ CD25+ tumor infiltrating T cells between both mice strains but an enhanced accumulation of CD4+ PD-1+ T cells in the lung tumors of STAT1 KO mice." (PMID 30647851, 2018). "However, studies have not currently ruled out the possibility that spatial heterogeneity of FoxP3+ cells in tumor samples may also be a contributing factor." (PMID 29320521, 2018). "However, it is notable that the CD8+/FOXP3+ ratio increased in all these studies which indicate the cytotoxic agents may modulate T cell infiltration irrespective of the tumor background." (PMID 30474571, 2018). "However, since it has been reported that Foxp3 protein was expressed in tumor cells and lymphocytes other than Treg cells, authentic Treg cells might not be detected by staining only for Foxp3." (PMID 30261082, 2018). "Changes in tumor microenvironment and metabolic reprogramming can affect not only the differentiation of primary T cells into Tregs, but also its immune suppression function, and therefore also the balance of Tregs and Th17 by affecting the expression of Foxp3 and RORgt." (PMID 30477520, 2018). "Unfortunately, we could not examine FOXP3 due to insufficient tumor samples." (PMID 29805739, 2018). "However, in our study, there was no relation between Foxp3 expression and tumor size." (PMID 28923073, 2017). "Besides FOXP3+CD4+ Treg cells, other immune cell types, such as NK cells, immunoregulatory APCs, MDSCs, and CD8+ regulatory cells, may affect tumor progression and directly or indirectly enhance T cell dysfunction." (PMID 28545567, 2017). "Moreover, it was found that the levels of CD4+CD25+FOXP3+ Treg cells in the peripheral blood of advanced (stage III-IV) HCC patients were higher than those of early (stage I-II) HCC patients, which implies that the presence of CD4+CD25+ Treg cells was closely related to tumor progression." (PMID 28796055, 2017). "However, tumor FOXP3 expression was not statistically correlated with any clinicopathologic features, though advanced pathologic stage (III-IV) seemed to be associated with high FOXP3 expression." (PMID 28716029, 2017). "Interestingly, the metastatic A9 tumour microenvironment stained intensely for suppressive T-regulatory cell marker (FoxP3+), while this was not seen in the A9+IL-33 expressing tumour environment or in the negative control that are also associated with tumour immune-resistance." (PMID 27619158, 2016).
tumor (continued). "Furthermore, because the lack of prognostic value for FOXP3 was a surprising finding due to previous reports on their adverse impact in tumor progression, we performed an additional analysis whereby total and stromal CD8 and FOXP3 expression were combined together." (PMID 27329602, 2016). "In addition, absolute Foxp3+ Treg cell numbers revealed a rapid increase compared with that of the other T cell subsets in the tumor sites, further confirming that Treg cells are the most dominant CD4+ T cell subset forming a tumor suppressive microenvironment at late stage of tumor progression." (PMID 25968569, 2015). "Whether functionally mature Tregs are recruited into the tumor microenvironment via cancer cell secreted chemokines or whether FoxP3 negative CD4+ T-cells are functionally converted into FoxP3+ Tregs by the cytokine milieu present within the tumor microenvironment is still controversial." (PMID 26690220, 2015). "Interestingly, although tumor infiltrating SKAP55 KO or ADAP KO CD8+ T cells, as well as CD4+ effector/memory T cells, substantially reduced PD-1 expression during anti-tumor response, we did not observe any significant changes in CTLA-4 expression or infiltrating CD4+Foxp3+ Tregs in vivo." (PMID 25851535, 2015). "Thus, tumor cells must carefully fine-tune their level of FOXP3 expression to balance these negative effects on growth against the putative positive effects of low level expression on immune escape, potentially explaining the conflicting reports regarding FOXP3 function in cancers." (PMID 24406338, 2014). "However, the intraepithelial FOXP3+ cell density in tumor nests was not prognostic." (PMID 24938080, 2014). "Therefore, we speculated Foxp3 +Tregs aggregate surrounding the tumor of BC were not merely dependent on CCL22 but via other chemotaxis." (PMID 24124553, 2013). "In summary, the results indicate that FOXP3-specific T cells generated in vitro using human FOXP3 RNA-transfected DCs as stimulators efficiently lyse SUM149 cells, however increased anti-apoptotic signaling may contribute to tumor cell resistance to T-cell mediated lysis." (PMID 23341929, 2013). "In this study we have also confirmed that FoxP3+ Treg-cells are highly accumulated in the microenvironment in CRC mouse model, supporting the notion that the presence of Treg-cells may allow the escape of tumor cells from immune surveillance by cytotoxic T lymphocytes in CRC patients." (PMID 21559338, 2011). "In tumor tissue, most of FoxP3+ cells locate in the parenchymal region, where the FoxP3+ cells are close to liver tumor cells, while in non-tumor tissue, the majority of FoxP3+ cells aggregate in the mesenchymal region (parenchyma: mesenchyma, 7∶5 in tumor vs. 5∶22 in non-tumor, P<0.001)." (PMID 21935436, 2011). "OT-II Foxp3EGFP mice are essentially devoid of nTreg, having transgenic CD4 T cells that recognize a class II-restricted epitope derived from ovalbumin; Foxp3 expression could not be detected in TIL or SPL in these mice when implanted with ovalbumin-transfected B16 tumor (B16-OVA)." (PMID 22112546, 2011). "In addition, regulatory functions in tumour immunity may not be restricted to FoxP3-positive Treg and includes certain myeloid-derived cells." (PMID 19698134, 2009). "Tumour-infiltrating CD4+ T cells, irrespective of FOXP3 expression, exhibited elevated CD25 levels, suggesting an activated state." (PMID 41514641, 2025). "Whereas depletion of CD4+CD25+Foxp3+ Tregs inhibited tumor growth and enhanced infiltration and function of CD8+ T cells in vivo, Gal1 knockdown failed to further improve the anti‐tumor effect in Treg‐depleted mice." (PMID 39853961, 2025). "Their findings also showed that treatment with an anti-CD25 antibody, which is widely used to deplete Foxp3+CD25+ Tregs in mice, failed to reduce tumor growth, likely due to the simultaneous depletion of tumor-specific CD8+ T cells." (PMID 40243581, 2025).
tumor (continued). "Further, this is the first study to show a prognostic value of both low FOXP3 TIL count and negative tumour cell PD-L1 expression in the same patient series." (PMID 39883679, 2025). "When accounting for various spatial relationships between immune and tumor cells in the multivariate analysis, CD8+FoxP3+PD-1+ cells did not independently correlate with OS, but its predictive power for PFS remained robust." (PMID 40422521, 2025). "Moreover, the gene expression analysis was performed on tumor bulk tissue without resolution of cell types and could not definitively attribute the expression of FOXP3 and PD-L1 to specific cell types, particularly since these molecules can be expressed in both immune and tumor cells." (PMID 40806346, 2025). "Of note, Foxp3+ Tregs did not efficiently infiltrate into the lung compared with effector CD4+ T cells, while tumor-infiltrating Treg cells highly expressed ICOS regardless of host age or anti–PD-L1 therapy." (PMID 40198121, 2025). "Their results indicated that FoxP3 expression was absent in MNG tissues, while a substantial presence of tumor-infiltrating FoxP3+ Tregs was observed in primary PTC and lymph node tissues." (PMID 40313970, 2025). "A statistically significant positive correlation was revealed between FoxP3 and CCL22 in S/M, but not between FoxP3 and CCL22 expressed by tumor cells." (PMID 39232378, 2024). "The number of FOXP3 positive cells was not different between patients’ samples who received three versus six cycles of NACT or between BRCAm/HRD and BRCA-WT tumours." (PMID 39578450, 2024). "We showed that no matter the phenotype, the number of CD3+, FoxP3+ or CD45RO+ cells was highly variable from one tumor to the other and these cells were on average more frequent at the tumor margin, although the difference was not statistically significant." (PMID 38887294, 2024). "Patients with positive SOX12, Foxp3, CD11b, and CD163 expression or negative CD8 expression showed tumor‐aggressive tendency and poor prognosis." (PMID 39072947, 2024). "The increase in FOXP3 positive cells in the NACT samples was seen in both BRCA-WT and BRCAm/HRD tumours, however, was not significant in the BRCAm/HRD group in the patients-matched cohort." (PMID 39578450, 2024). "Strikingly, in inflammation-induced AOM/DSS tumors, we found increased infiltration of CD4+ T cells and FOXP3+ Tregs, but not of CD8+ cells or F4/80+ macrophages into FibΔZeb1 tumors, indicating modulation of adaptive anti-tumor immunity." (PMID 38937629, 2024). "Evaluating PD-L1 expression and TILs in the TME, significant correlation between PD-L1 IC and CPS, but not TPS and the number of tumour-infiltrating CD4+ T cells, Foxp3+CD4+ T cells, and CD8+ T cells were detected." (PMID 38541208, 2024). "However, we could not detect any CD8+FoxP3+ T cells, neither in the stroma nor in the tumor mass." (PMID 36900249, 2023). "Cellular neighborhood N3 was associated with tumors with no recurrence and was enriched for FOXP3 + regulatory T cells, CD8 + T cells, high PD-1 protein levels, stromal cells, and tumor cells." (PMID 36959234, 2023). "FOXP3+ cells connected to good prognosis in the analysis of OS/no notable correlations between CD3+ and CD8+ cells and the tumor’s clinical characteristics." (PMID 38077386, 2023). "NACT significantly increased infiltrates of CD4+Foxp3+ Treg cells (P = 0.036) and PD-L1+CD68+ macrophages (P = 0.022) in the stroma and decreased M1/M2 ratio (P = 0.016) in the tumor of CRS1 non-responders." (PMID 36993949, 2023). "In another trial that did not differentiate by tumor type, the significance of the ratio of CD8+ to FoxP3+ T cells to DFS was validated." (PMID 37511876, 2023). "Although the current study shows that CD8+FOXP3+ T cells are a special class of exhausted CD8+ T cells, the specific mechanism of action of tumor microenvironment inducing CD8+ T-cell exhaustion is not clear." (PMID 38066053, 2023).